LAG3 (lymphocyte activating 3)
Diseases named in the same sentence as LAG3 in open-access papers (continued):
Sharing a sentence is not in itself a finding about the gene and the disease.
HCMV infection (4 papers, 2019 to 2025). "Furthermore, and in line with our previous data, the LAG-3/PD-1 blockade restore the ability of KIRpos NK cells from R to control the in vitro HCMV infection after 48 hours of coculture." (PMID 34003794, 2021). "This apparent paradox of concomitant high levels of HCMV infection and high numbers of CD8+ T cells as a risk factor for severe brain lesions prompted us to measure the expression of the immune checkpoint receptors PD-1/PD-L1 and LAG-3." (PMID 31991822, 2020). "The adaptive-like NK cells featured high expression of CD3E, LAG3, and IL-32 with no expression of FCER1G and TCRs, consistent with published scRNA-seq data (except for low expression of KLRC2/NKG2C, the canonical markers for adaptive NK cells after human cytomegalovirus (HCMV) infection) 21,22." (PMID 40394087, 2025).
hepatitis B (4 papers, 2017 to 2024). "The role of soluble LAG-3 (sLAG-3) in hepatitis B infection is poorly investigated." (PMID 37056774, 2023).
leprosy (4 papers, 2017 to 2022). Leprosy is a chronic infectious disease affecting primarily the skin and peripheral nervous system. "Therefore, we hypothesized that PD-1 and LAG3 T lymphocyte inhibition receptors (also known as CD279 and CD223, respectively) could be part of the suppression strategy, linked to greater susceptibility to infectious diseases such as leprosy." (PMID 33777045, 2021). "Here, expression of two receptors (PD-1 and LAG3) related to the suppression mechanisms of Treg cells does not appear to be associated to age in leprosy patients." (PMID 33777045, 2021). "When comparing leprosy patients to HHC, 16 genes showed significantly different expression for leprosy patients (increased: FCGR1A, IL6, IL15, LRKK2, MBP, MSR1, PACRGv1, TLR1, TLR4; decreased: CAMTA, CD3E, CTLA4, CXCL13, GATA3, LAG3, TFGB)." (PMID 31784594, 2019). "In leprosy patients, the role of LAG-3 remains unknown, although LAG-3+CD8+ T cells were detected when human PBMC cells were cultured with M. leprae as well as in human mycobacteria-induced granulomas." (PMID 29312289, 2017). "We also observed changes in gene expression of the LAG3 and PDCD1 receptors in cutaneous lesions of young MB patients and not in elderly leprosy patients." (PMID 33777045, 2021).
non-Hodgkin lymphoma (4 papers, 2023 to 2024). Distinct from Hodgkin lymphoma both morphologically and biologically, non-Hodgkin lymphoma (NHL) is characterized by the absence of Reed-Sternberg cells, can occur at any age, and usually presents as a localized or generalized lymphadenopathy associated with fever and weight loss. "In a phase I clinical trial of the anti-LAG3/anti-PD1 bispecific tebotelimab, objective responses were observed in multiple solid tumor types, including PD1-refractory disease, and in LAG3+ non-Hodgkin lymphomas." (PMID 38556085, 2024). "There were tumor decreases in 34% (59/172) of response-evaluable patients in the dose-escalation cohorts, with objective responses in multiple solid tumor types, including PD-1-refractory disease, and in LAG-3+ non-Hodgkin lymphomas, including CAR-T refractory disease." (PMID 37857711, 2023).
oesophageal adenocarcinoma (4 papers, 2020 to 2022). "In patients diagnosed with locally advanced esophageal adenocarcinoma, the complete pathological response (CR), LAG-3 and CXCL9 were more predictive than CR alone in terms of DFS, which is correlated with the reduced rate of recurrence." (PMID 35669786, 2022). "In summary, LAG-3 may act as a promising biomarker for locally advanced esophageal adenocarcinoma." (PMID 35669786, 2022). "The frequency and distribution of LAG3 expression in oesophageal adenocarcinoma (EAC) is unknown." (PMID 32592066, 2020). "However, it was reported that LAG3 expression was associated with an improved overall survival (OS) compared to patients without LAG3 expression in oesophageal adenocarcinoma." (PMID 35530341, 2022).
pulmonary TB (4 papers, 2016 to 2025). "First, studies have confirmed a link between CD4 + TEM cell markers (GBP2 and LAG3) and the risk of pulmonary TB and COVID-19 infection, as the lungs are the primary sites affected by TB, and CD4 + T cells are closely related to TB." (PMID 40295296, 2025). "The overexpression of LAG-3 gene was found as a potentially important characteristic of both pulmonary TB (PTB) and extrapulmonary TB (EPTB)." (PMID 38957797, 2024). "In patients with pulmonary TB, similar patterns of T‐cell dysfunction have been observed in granulomatous tissues, where overexpression of inhibitory molecules (e.g., PD‐1 and LAG‐3) may contribute to immune suppression." (PMID 40746087, 2025). "LAG3 was recently shown to be highly expressed in the lungs of macaques with active pulmonary TB and not in latent TB infection, suggesting a link between low LAG3 expression and successful containment of M. tb infection." (PMID 27301245, 2016).
acute lymphoblastic leukemia (3 papers, 2021 to 2025). Leukemia with an acute onset, characterized by the presence of lymphoblasts in the bone marrow and the peripheral blood. "Furthermore, B7-H3+LAG3+ CD4+ T cells were induced during co-culture with bone marrow cells from pediatric patients with B-cell acute lymphoblastic leukemia (B-ALL)." (PMID 40070836, 2025). "Finally, to assess B7-H3 and LAG3 expression on CD4 CTLs in human tumor tissues, we analyzed bone marrow aspirates from twelve pediatric patients diagnosed with B-cell acute lymphoblastic leukemia (B-ALL)." (PMID 40070836, 2025).
adrenocortical carcinoma (3 papers, 2022 to 2024). "No studies at all are reported on LAG3 and thymoma, nor LAG3 and adrenocortical carcinoma." (PMID 36224560, 2022).
Allergy (3 papers, 2016 to 2021). An allergy is an immune response or reaction to substances that are usually not harmful. "Both PPG/LPA-stimulated FOXP3, and PPG-stimulated LAG3, gene expression levels were lower in the neonates with maternal allergies than in the neonates from mothers without allergies (P < 0.05)." (PMID 27646403, 2016).
bipolar disorder (3 papers, 2023 to 2025). A disorder of the brain that causes unusual shifts in mood, energy, activity levels and the ability to carry out day-to-day tasks. "It has also been reported that the expression of LAG-3 is associated with activated microglia in the hippocampus of patients with bipolar disorder." (PMID 38026700, 2023). "Similarly, LAG3, a microglial checkpoint, has been linked to suicide in bipolar disorder patients due to reduced LAG3 expression." (PMID 40536592, 2025). "Moreover, the proportion of microglia expressing Lag3 is diminished in patients with bipolar disorder that are suicidal, highlighting a potential role of Lag3 in neuroimmune dysfunction." (PMID 41177809, 2025).
brain tumors (3 papers, 2019 to 2023). "Separately, dysregulation of checkpoint markers, such as PD-L1, PD-1, LAG-3, and TIM-3, have been implicated in immune suppression, although the exact relationship of these markers to brain tumor-mediated immune suppression remains unclear." (PMID 31938638, 2019).
cholangiocarcinoma (3 papers, 2022 to 2024). A carcinoma that arises from the intrahepatic biliary tree (intrahepatic cholangiocarcinoma) or from the junction, or adjacent to the junction, of the right and left hepatic ducts (hilar cholangiocarcinoma). "Therefore, PD-1 and EOMES represent two independent exhaustion pathways in all three types of cholangiocarcinoma; and other T cell exhaustion markers including LAG3, TIM3, TOX were thus investigated below." (PMID 35346322, 2022).
chronic hepatitis B (3 papers, 2017 to 2024). "Increased LAG-3 expression was reported to suppress T-cell function in chronic hepatitis B. Previous studies have demonstrated that LAG-3 can suppress the CD8+ T-cell response in chronic viral infection." (PMID 38343550, 2024). "The results showed that LAG-3 expression levels were significantly higher in CD8+ T cells from chronic hepatitis B patients in the immune-active phase compared with chronic asymptomatic HBV carriers and healthy controls." (PMID 28072682, 2017). "The state of LAG-3 expression and the inhibitory effect of LAG-3 on CD8+ T-cell function in chronic hepatitis B (CHB) patients remain unclear." (PMID 28072682, 2017). "After blocking PD-L1 and LAG-3, CD4+ T cell function in chronic hepatitis B patients was partially restored." (PMID 31390978, 2019). "After blocking PD-L1 and LAG-3, the function of CD4+ T cells in chronic hepatitis B patients can be partially restored." (PMID 31390978, 2019).
classic Hodgkin lymphoma (3 papers, 2022 to 2025). Classical Hodgkin lymphoma (CHL) is a B-cell lymphoma characterized histologically by the presence of large mononuclear Hodgkin cells and multinucleated Reed-Sternberg (HRS) cells. "LAG-3 expression in distinct tumor-infiltrating lymphocyte (TIL) subpopulations, particularly in tumors with low MHC-II expression, may be critical for the development of a tolerogenic immune environment in classic Hodgkin lymphoma (cHL)." (PMID 41357215, 2025).
graft versus host disease (3 papers, 2023 to 2025). An immune system disorder that occurs after allogeneic hematopoietic stem cell transplant and is a reaction of donor immune cells against host tissues. "LAG3 is typically associated with Tregs and immune tolerance, preventing immune-mediated inflammation such as graft versus host disease." (PMID 40070836, 2025). "In line with our findings, a previous study showed that LAG3-KO CD4+ T cells secrete significantly more IFN-γ and IL-10 than WT CD4+ T cells in murine graft-versus-host disease." (PMID 37172058, 2023).
Granuloma (3 papers, 2017 to 2019). A compact, organized collection of mature mononuclear phagocytes, which may be but is not necessarily accompanied by accessory features such as necrosis. "Consistent with our findings in peripheral blood of humans, expression of the inhibitory receptors CTLA-4, PD-1, and LAG-3 was very low on T cells isolated from granulomas of Mtb-infected macaques and did not correlate with Mtb bacterial load." (PMID 31497018, 2019).
Helminth infection (3 papers, 2018 to 2024). "Helminth infections, including B. malayi infections, produce exhausted T cells with increased expression of inhibitory receptors (PD-1, LAG3, CTLA4) that are capable of downregulating T-cell proliferative responses and increasing the potential for apoptosis." (PMID 39434874, 2024). "Helminth infection modulates host T cell function through multiple factors including induction of Tregs, IL-10/TGF-β regulatory cytokines, PD-1/PD-L, and other co-inhibitory molecules such as LAG-3, BTLA-4, CTLA-4, Tim-3, etc.." (PMID 30093899, 2018).
Hypertension (3 papers, 2021 to 2022). The presence of chronic increased pressure in the systemic arterial system. "No DLTs were associated with anti-LAG3 monotherapy, while five total DLTs were observed in combination arms of anti-LAG-3 + nivolumab (one grade 3 muscle weakness, two a grade 3/4 edema, one grade 3 hypertension, and one grade 3 syncope)." (PMID 33810532, 2021).
hypophysitis (3 papers, 2024 to 2025). Inflammation of the pituitary gland. "Furthermore, the risk of polyendocrinopathy appears to be elevated when LAG-3 inhibitors are used in combination with PD-1 blockade, with reported occurrences of adrenalitis, hypophysitis, and thyroiditis." (PMID 40895685, 2025). "A recent study has shown that combination therapy with LAG-3 and PD-1 inhibitors resulted in a higher incidence of hypophysitis than PD-1 inhibitor monotherapy (2.5% vs. 0.8%, respectively)." (PMID 38915406, 2024). "Although LAG-3 inhibitors have not been adequately studied with respect to hypophysitis risk, the addition of a LAG-3 inhibitor to a PD-1 inhibitor appears to raise the incidence of hypophysitis from 0.8% to 2.5%." (PMID 41002414, 2025).
hypothyroidism (3 papers, 2022 to 2024). Abnormally low levels of thyroid hormone. "The p.Pro67Thr variant could be acting as an inhibitor of LAG3 immunoregulatory activity, which in turn leads to susceptibility to hypothyroidism." (PMID 36653562, 2023). "The relationship between checkpoint inhibition and hypothyroidism in clinical practice, alongside observing individual associations to CTLA4 and LAG3, encouraged us to look further at the role of genetic predisposition." (PMID 39041034, 2024). "A common side effect of immune checkpoint inhibitors, including those that target LAG3, is hypothyroidism." (PMID 36653562, 2023).
inflammatory bowel disease (3 papers, 2019 to 2021). A spectrum of small and large bowel inflammatory diseases of unknown etiology. "In patients with inflammatory bowel disease, LAG-3 expressing T cells are primarily found at sites of mucosal inflammation and their numbers correlate with disease activity." (PMID 34108957, 2021).
kidney cancer (3 papers, 2024 to 2025). Primary or metastatic malignant neoplasm involving the kidney. "Common immune checkpoints in kidney cancer (PD-1, CTLA4 and LAG3) were more significantly expressed in the high-risk group." (PMID 38546385, 2024). "Next, the RT-PCR results of existing kidney cancer cell lines in the laboratory found LAG3 to be highly expressed in 786-O and ACHN cell lines, which were selected for subsequent validation." (PMID 38291496, 2024). "Additionally, LAG3 CNV was associated with poor survival in PCPG and KICH; CXCL13 in kidney cancers (KIRC and KIRP) and MESO; LAYN in KIRP, SARC and LGG." (PMID 40076932, 2025). "We believe our findings will provide a preliminary basis and direction for LAG3-targeted immunotherapy and even CAR-T therapy in patients with kidney cancer." (PMID 38291496, 2024). "An analysis of the CCLE dataset revealed a significantly high expression of LAG3 in A-704, OS-RC-2, SNU-349, KMRC-3, SLR 26, and ACHN kidney cancer cell lines." (PMID 38291496, 2024). "Higher expression of LAG3, PDCD1, and TIGIT showed the worst survival outcome of anti-ICB therapy in kidney cancer indication drug resistance, whereas high LAG3 and CXCL13 expressions were associated with better survival of anti-PDL1 therapy in metastatic BLCA, indicating drug sensitivity." (PMID 40076932, 2025).
latent infections (3 papers, 2018 to 2022). "However, on days 23 to 41, during latent infection, the number of both LAG-3+CD8+ T cells and PD-1+CD8+ T cells started to decline." (PMID 30619285, 2018).
malignant pleural mesothelioma (3 papers, 2019 to 2023). A malignant neoplasm that arises from mesothelial cells in the pleura and shows a diffuse growth pattern. "In both pleural and peritoneal effusions of patients with malignant pleural mesothelioma, LAG-3+ NK-cells can be found, but the expressions vary strongly between patients (1.0 –68.1% LAG-3+ NK-cells of all NK-cells)." (PMID 34276685, 2021). "The role of LAG3and ICIs of LAG3 are unknown in malignant pleural mesothelioma (MPM)." (PMID 38062416, 2023).
myocardial infarction (3 papers, 2021 to 2025). Gross necrosis of the myocardium, as a result of interruption of the blood supply to the area, as in coronary thrombosis. "Deficiency of the immune checkpoint lymphocyte activation gene-3 (LAG3) protein is significantly associated with both elevated HDL-cholesterol (HDL-C) and myocardial infarction risk." (PMID 35501457, 2022). "The investigation of alternative immune checkpoint targets, such as lymphocyte activation gene 3 (LAG-3) and CD47, has gained momentum as a potential strategy for cardiovascular protection, particularly after myocardial infarction (MI)." (PMID 41383640, 2025).
pancreatic adenocarcinoma (3 papers, 2021 to 2024). "When correlating the expression of IDO, VISTA, LAG3, and TIM3 with survival, we unexpectedly found IDO-positive tumors associated with a significantly longer overall survival (OS) in patients with resected pancreatic adenocarcinomas." (PMID 34072549, 2021). "“Profile-B” is made by the 6 molecules differently expressed in Pancreatic adenocarcinoma (PAAD) patients (i.e., TIM3 (HAVCR2), OX40 (TNFRSF4), GITR (TNFRRSF18), TIGIT, LAG3 and CTLA4)." (PMID 36224560, 2022).
pneumonitis (3 papers, 2020 to 2023). An inflammatory process affecting the lung parenchyma. "By contrast, PD-1 and LAG-3 blockade more often result in pneumonitis and joint affection." (PMID 35784333, 2022).
skin tumors (3 papers, 2020 to 2025). "In addition, this T-cell cluster exhibited over-expression of exhaustion marker genes such as Tox, Pdcd1, Tigit, Havcr2, Lag3, and Ctla4 in the T cell cluster in skin tumors, suggesting the emergence of T-cell exhaustion in skin tumors." (PMID 40282557, 2025). "Interestingly, we found Pd‐1 and its ligands Pd‐l1 and Pd‐l2 as well as Tigit, Tim3, and Cd226 to be significantly upregulated in skin tumors, whereas Lag3 and Cd96 were not significantly changed compared to control skin." (PMID 32615027, 2020).
stomach adenocarcinoma (3 papers, 2019 to 2022). "Besides PD-L1, PD-L2, PD-1, CD80, CD86, CTLA-4, Tim-3, LAG3, and 4-1BB, we found the increase of an inducible co-stimulator (ICOS) expression in both HPV-positive head and neck squamous cell carcinoma and EBV-positive stomach adenocarcinoma tumors." (PMID 30911684, 2019).
acute GVHD (2 papers, 2018 to 2023). "The presence of the LAG3 rs870849 TT genotype was associated with an increased risk of severe acute GVHD independently of the PDCD1 rs36084323 genotype." (PMID 36742309, 2023). "Our findings show that patients transplanted from donors homozygous for the T allele at the LAG-3 rs870849 SNP have an increased risk of severe acute GVHD, increased TRM and worse survival." (PMID 36742309, 2023). "Multivariate analysis confirmed that LAG3 rs870849 TT genotype of the donor was an independent risk factor for a higher incidence of acute GVHD, independently of the PDCD1 genotype (p: 0.031; HR: 1.76, 95%CI: 1.05 – 2.94)." (PMID 36742309, 2023). "Multivariate analysis with regression modeling of competing risks identified the LAG3 rs870849 TT genotype of the donor as an independent risk factor for developing severe acute GVHD (p: 0.047; hazard ratio [HR]: 1.64, 95% confidence interval [CI] 1.01 – 2.67)." (PMID 36742309, 2023). "However, if this hypothesis is true, the rs870849 T allele (coding for Isoleucine) should be associated with a higher inhibitory activity of LAG3 and therefore with a lower incidence of acute GVHD in the allogeneic model, which is just opposite to our findings." (PMID 36742309, 2023). "When combining the LAG3 rs870849 and the PDCD1 rs36084323 genotypes of the donor, three genetic groups were well defined, allowing a good stratification of the risk of acute GVHD, TRM, OS and DFS." (PMID 36742309, 2023). "In acute graft-versus-host disease (GVHD), both human and murine experimental evidence demonstrates that co-blockade using tetravalent CTLA-4-Ig and LAG-3-Ig could synergistically suppress T cell responses, prevent acute GVHD, and decrease GVHD fatality rates as well." (PMID 30603054, 2018).
anaplastic thyroid cancers (2 papers, 2022 to 2025). "Within anaplastic thyroid cancer there is a strong positive correlation between LAG-3 and PDL-1 expression, but only in male patients." (PMID 36077354, 2022). "Conversely, an anaplastic-thyroid-cancer (ATC) compendium uncovered pervasive CD8+-T-cell exhaustion (PD-1/LAG-3/TIM-3 co-expression) and M2-skewed macrophages, nominating dual PD-1+ LAG-3 blockade or macrophage-reprogramming as rational combinations for these “cold” tumours." (PMID 40959084, 2025).
anemia (2 papers, 2025 to 2026). A reduction in the number of red blood cells, the amount of hemoglobin, and/or the volume of packed red blood cells. "Anemia and hypercalcemia prevailed in the LAG3 r2870849 carriers (T455hom and I455Thet)." (PMID 41614836, 2025).
astrocytoma (2 papers, 2023 to 2025). "However, in the TCGA astrocytoma cohort, there was a negative association of A2AR with PD-L1, TIM-3, and HLA-DQA1, and only a positive correlation with LAG-3." (PMID 37047660, 2023).